MIR3164 (microRNA 3164)
Synonyms: hsa-mir-3164
Gene: MicroRNA gene on chromosome 11 (69,083,176 to 69,083,258, forward strand). Ensembl gene ENSG00000265539.
Homologues: Orthologues: chimpanzee MIR3164 (100% identical).